ZBTB12 (zinc finger and BTB domain containing 12)
Description:
May be involved in transcriptional regulation.
Synonyms: C6orf46; G10; NG35; D6S59E; Bat9
Tractability: PROTAC: ubiquitination databases record sites on it.
Gene: Protein-coding gene on chromosome 6 (31,899,613 to 31,902,086, reverse strand). Ensembl gene ENSG00000204366.
Subcellular location: Nucleus
Subcellular location (Human Protein Atlas): Nucleoplasm
Gene Ontology:
Molecular function: protein binding; sequence-specific double-stranded DNA binding; DNA-binding transcription repressor activity, RNA polymerase II-specific; RNA polymerase II cis-regulatory region sequence-specific DNA binding
Biological process: negative regulation of transcription by RNA polymerase II; regulation of cytokine production; regulation of immune system process
Cellular component: nucleoplasm; nucleus
Genetic constraint (gnomAD): Loss-of-function variants: 3 observed, 10.54 expected, observed/expected ratio (o/e) 0.28, 90% interval 0.13 to 0.74. The upper end of that interval is the gene's LOEUF score, 0.74, which puts it in group 3 of 6, group 1 being the genes least tolerant of losing a copy. Missense variants: 344 observed, 625.78 expected, observed/expected ratio (o/e) 0.55, 90% interval 0.5 to 0.6. Synonymous variants: 273 observed, 268.93 expected, observed/expected ratio (o/e) 1.02, 90% interval 0.92 to 1.12.
Homologues: Orthologues: macaque ZBTB12 (99% identical), chimpanzee ZBTB12 (99% identical), pig ZBTB12 (99% identical), dog ZBTB12 (98% identical), rat Zbtb12 (98% identical), mouse Zbtb12 (97% identical), tropical clawed frog zbtb12 (60% identical), zebrafish zbtb12.2 (42% identical), zebrafish zbtb12.1 (36% identical). Paralogues in human: ZBTB6 (29% identical), ZBTB26 (29% identical), BCL6 (24% identical), BCL6B (21% identical), ZBTB46 (19% identical), ZBTB21 (18% identical), ZBTB7B (17% identical), ZBTB49 (16% identical), NACC2 (16% identical), ZBTB14 (16% identical), NACC1 (15% identical), GFI1 (15% identical), and 16 more.
Diseases named in the same sentence as ZBTB12 in open-access papers:
ZBTB12 is named in the same sentence as 9 diseases in open-access papers, as found by Europe PMC text mining. Sharing a sentence is not in itself a finding about the gene and the disease. The quoted sentences say what the papers report.
myocardial infarction (3 papers, 2019 to 2025). Gross necrosis of the myocardium, as a result of interruption of the blood supply to the area, as in coronary thrombosis. "For instance, differentially methylated regions (DMRs) at the ZBTB12 gene and LINE-1 elements in white blood cells have been associated with an increased risk of myocardial infarction (MI)." (PMID 40296161, 2025). "They identified a differentially methylated region within the gene body of Zinc Finger and BTB Domain Containing 12 (ZBTB12), which was hypermethylated in myocardial infarction cases compared to controls." (PMID 40076974, 2025).
colorectal cancer (1 paper, 2023). A primary or metastatic malignant neoplasm that affects the colon or rectum. "Our data show the prognostic value of ASPHD1 and ZBTB12 in CRC, warranting further investigations to validate their clinical potential as prognostic markers and predictive markers for colorectal cancer." (PMID 37686578, 2023).
diabetes (1 paper, 2019). "We first studied the association of ZBTB12 methylation factors with a number of classical CVD risk factors, including physical activity, smoke, hypertension, dyslipidemia, obesity, diabetes, and alcohol consumption." (PMID 31077224, 2019).
glioma (1 paper, 2026). A benign or malignant brain and spinal cord tumor that arises from glial cells (astrocytes, oligodendrocytes, ependymal cells). "Furthermore, specific mutations in HUSE.017 and HUSE.050 increased the predicted binding of ZFP57 and zinc finger and BTB domain-containing 12 (ZBTB12), two TFs linked to chromatin remodeling and transcriptional repression in gliomas." (PMID 41019514, 2026).
cardiovascular disease (2 papers, 2019 to 2024). "ZBTB12 hypomethylation is linked to shorter TNF-ɑ stimulated whole blood coagulation time and increased WBC and granulocyte counts, further elucidating the possible link between ZBTB12 methylation and cardiovascular disease risk." (PMID 31077224, 2019). "In addition, ZBTB12 plays important roles in various biological functions, such as serving as a molecular barrier that protects the unidirectional transition from the fate of metastable stem cells to the late developmental stage, and ZBTB12 methylation is associated with cardiovascular disease risk." (PMID 39518882, 2024). "However, the role of ZBTB12 in the pathogenesis of MI and cardiovascular disease in general is not yet clarified." (PMID 31077224, 2019).
cancer (1 paper, 2023). A tumor composed of atypical neoplastic, often pleomorphic cells that invade other tissues. "Collectively, ASPHD1 and ZBTB12 are linked to multiple proteins and genes which are associated with cancer initiation and progression." (PMID 37686578, 2023). "Similarly, cancers with high ZBTB12 expression were associated with poor patient survival compared to cancers with low ZBTB12 expression (p < 0.05)." (PMID 37686578, 2023).
ZBTB12 also shares sentences with these, for which no sentence is quoted: dyslipidemia (1 paper); Hypertension (1); Obesity (1).